HCN4 (hyperpolarization activated cyclic nucleotide gated potassium channel 4)
Description:
Hyperpolarization-activated ion channel that are permeable to Na(+) and K(+) ions with very slow activation and inactivation. Exhibits higher selectivity for K(+) over Na(+) ions. Contributes to the native pacemaker currents in heart (If) that regulate the rhythm of heart beat (Probable). Contributes to the native pacemaker currents in neurons (Ih) (Probable). May mediate responses to sour stimuli (By similarity).
Synonyms: BRGDA8; EIG18; SSS2
Tractability: Small molecule: an approved drug acts on it; a structure with a bound ligand is known; a high-quality ligand is known; it has a binding pocket of medium quality; it belongs to a druggable protein family. Antibody: UniProt places it where antibodies can reach, with high confidence; its Gene Ontology location is reachable by antibodies, with high confidence; UniProt predicts a signal peptide or a membrane-spanning region. PROTAC: its protein half-life has been measured; a small molecule that binds it is known.
Target class: Ion channel; Voltage-gated ion channel; Cyclic nucleotide-regulated channel
Gene: Protein-coding gene on chromosome 15 (73,319,859 to 73,368,958, reverse strand). Ensembl gene ENSG00000138622.
Subcellular location: Cell membrane
Pathways (Reactome):
Neuronal System: HCN channels
Gene Ontology:
Molecular function: identical protein binding; intracellularly cAMP-activated cation channel activity; protein binding; voltage-gated potassium channel activity; voltage-gated potassium channel activity involved in SA node cell action potential depolarization; voltage-gated sodium channel activity; monoatomic ion channel activity; sodium channel activity
Biological process: cellular response to cAMP; cellular response to cGMP; membrane depolarization during SA node cell action potential; monoatomic cation transport; potassium ion import across plasma membrane; potassium ion transmembrane transport; regulation of cardiac muscle cell action potential involved in regulation of contraction; regulation of cardiac muscle contraction; regulation of heart rate; regulation of heart rate by cardiac conduction; regulation of membrane depolarization; regulation of membrane potential; SA node cell action potential; sodium ion import across plasma membrane; sodium ion transmembrane transport; blood circulation; membrane depolarization during cardiac muscle cell action potential; muscle contraction; regulation of SA node cell action potential; sinoatrial node development; monoatomic ion transport; potassium ion transport; transmembrane transport
Cellular component: HCN channel complex; perinuclear region of cytoplasm; plasma membrane; axon; dendrite; membrane
Genetic constraint (gnomAD): Loss-of-function variants: 29 observed, 69.19 expected, observed/expected ratio (o/e) 0.42, 90% interval 0.31 to 0.57. The upper end of that interval is the gene's LOEUF score, 0.57, which puts it in group 2 of 6, group 1 being the genes least tolerant of losing a copy. Missense variants: 1,362 observed, 1,498.8 expected, observed/expected ratio (o/e) 0.91, 90% interval 0.87 to 0.95. Synonymous variants: 751 observed, 658.79 expected, observed/expected ratio (o/e) 1.14, 90% interval 1.07 to 1.21.
Gene-disease validity (ClinGen):
ClinGen rates the evidence that HCN4 causes each of these diseases.
sick sinus syndrome 2, autosomal dominant (autosomal dominant): Definitive.
Brugada syndrome 1 (autosomal dominant): Disputed.
Homologues: Orthologues: chimpanzee HCN4 (99% identical), macaque HCN4 (99% identical), pig HCN4 (96% identical), rat Hcn4 (95% identical), mouse Hcn4 (95% identical), guinea pig HCN4 (93% identical), dog HCN4 (79% identical), rabbit HCN4 (68% identical), zebrafish hcn4 (60% identical), zebrafish hcn4l (50% identical), Drosophila melanogaster Cngl (18% identical), Drosophila melanogaster Elk (14% identical), and 9 more. Paralogues in human: HCN2 (47% identical), HCN1 (46% identical), HCN3 (44% identical), KCNH2 (15% identical), KCNH7 (15% identical), KCNH8 (14% identical), KCNH5 (14% identical), KCNH4 (14% identical), KCNH3 (14% identical), CNGB1 (14% identical), CNGA3 (14% identical), KCNH1 (14% identical), and 5 more.
Diseases named in the same sentence as HCN4 in open-access papers:
HCN4 is named in the same sentence as 83 diseases in open-access papers, as found by Europe PMC text mining. Sharing a sentence is not in itself a finding about the gene and the disease. The quoted sentences say what the papers report.
Arrhythmia (25 papers, 2016 to 2025). Any cardiac rhythm other than the normal sinus rhythm. "Previous studies have only suggested that HCN4 is related to arrhythmia or heart failure, and this study is the first to find that HCN4 defects can cause simultaneously the clinical presentation of bradycardia, LVNC, and multiple valvular heart disease." (PMID 40613349, 2025). "This suggests that other factors, possibly upstream of HCN4 or in parallel pathways, contribute to the variations in SN function and arrhythmia susceptibility between the sexes." (PMID 39703520, 2024). "Although sinus bradycardia has been reported in relation to LQTS or HCN4 mutations, mutations in HCN4 are known to be associated with arrhythmias in which QT prolongation is rare." (PMID 36244448, 2022). "Here, we identified a HCN4 mutation, HCN4-R666Q, in two sporadic arrhythmia patients with sinus bradycardia, QT prolongation, and short bursts of ventricular tachycardia." (PMID 36244448, 2022). "This potentially implicates gain-of-function variants in HCN2 and HCN4 with increased pacemaker activity resulting in ectopic foci and cardiac arrhythmia." (PMID 33868385, 2021). "Arrhythmias associated with HCN4 mutations can be complex, but the majority of reported mutations are loss-of-function and are associated with bradycardia, in agreement with the funny channel involvement in rate control." (PMID 32038284, 2019). "It has been shown that Hcn4-related inheritable arrhythmias, resulting in four different mutations of the Hcn4 gene, are associated with reduced heart rate and various arrhythmias." (PMID 30246030, 2018). "HCN4 channels mediate pacemaker activity in the heart and many mutations associated with cardiac arrhythmias have been characterized." (PMID 30127718, 2018). "Mutation of HCN4 in humans is associated with cardiac arrhythmias and the inducible, and cardiac-specific, Hcn4 knockout in mice leads to severe bradycardia, cardiac arrest, and death." (PMID 28426719, 2017). "In a postmyocardial infarction animal model, ventricular upregulation of HCN4 causes a high volume of ventricular ectopic beats and potentially prolonged ventricular arrhythmias." (PMID 27747100, 2016). "Our findings provided new insights into the pathogenesis of arrhythmias related to HCN4 mutations." (PMID 36244448, 2022). "While HCN4 variants have been frequently associated with cardiac arrhythmias, these data represent the first experimental evidence that functional alteration of HCN4 can also be involved in human epilepsy through a loss-of-function effect and associated increased neuronal excitability." (PMID 30127718, 2018). "Our study revealed that MG132 may partly rescue the arrhythmia caused by HCN4-R666Q mutation." (PMID 36244448, 2022). "Thus HCN4 mutation-linked arrhythmias, too, provide evidence confirming the pacemaking role of If." (PMID 32038284, 2019). "In parallel with the increased expression of HCN4 protein and other potential arrhythmia promoters discussed previously, the incidence of ventricular electrical stimulation-induced ventricular fibrillation also increased in trained animals." (PMID 36815557, 2023). "Deletion of HCN4 in adult mice eliminated most of the SAN If current, causing cardiac arrhythmia characterized by recurrent sinus pauses and bradycardia; this suggested that HCN4 channels are essential for normal heart impulse generation and conduction." (PMID 37121973, 2023). "Most of these variants were located in genes associated with inherited arrhythmias and arrhythmic cardiomyopathies, such as MYBPC3, KCNQ1, TTN, CASQ2, GPD1L, DPP6, HCN4 and NEXN." (PMID 36008935, 2022).
Arrhythmia (continued). "Although HCN4 and GIRK4 loss-of-function variants have each been implicated in SND, the combination of silencing both genes seems to repair severe cardiac arrhythmia phenotype of SND associated with AV block and ventricular arrhythmia." (PMID 33868385, 2021). "HCN4 gene-related arrhythmias, including atrioventricular block and AF, have still an unexplored role in arrhythmogenesis, although HCN4 gene (cyclic nucleotide gated 4 channel) is generally accepted as a genetic marker in myocardial pacemaker tissues." (PMID 32477118, 2020). "Up-regulation of HCN4 gene expression in patients with acquired arrhythmias such as heart failure, cardiac hypertrophy, and atrial fibrillation increased the funny current and leaded to arrhythmias." (PMID 36440047, 2022). "Approximately 2–3 months after tamoxifen‐induced deletion of Ndufs4, 87.5% of the HCN4–Ndufs4−/− mice developed various forms of arrhythmia, including atrial or ventricular premature contractions, sinus bradycardia and frequent sinus pauses resembling those found in germline Ndufs4−/− LS mice." (PMID 35872650, 2022). "Abnormalities of HCN4 may result in a variety of arrhythmias, such as atrial fibrillation, sick sinus syndrome." (PMID 31921308, 2019). "MiR-1 is the most abundant microRNA in the adult mouse heart, accounting for 35–40% of the total amount of miRNA MiR-1 directly targets connexin-43, KcnJ2, Kcne1, Ncx1, PP2A/RyR2, and Hcn4 in the adult heart, contributing to the arrhythmias that we and others observed in miR-1 TG adult hearts." (PMID 30936836, 2019). "No other pathogenic mutations in the known arrhythmia-related genes were found in the two patients, suggesting that the loss of function of the HCN4 mutation might be associated with sinus bradycardia, QT prolongation, and short bursts of ventricular tachycardia." (PMID 36244448, 2022).
Bradycardia (23 papers, 2015 to 2025). A slower than normal heart rate (in adults, slower than 60 beats per minute). "Previous studies of SCN5A p.E1784K describe frequent bradycardia in the carriers; at the same time, the HCN4 gene is known to be associated with sinus rhythm disorders and bradyarrhythmia." (PMID 40299689, 2025). "It was inferred that this novel HCN4 variant is associated with the clinical presentation of bradycardia, LVNC, and multiple valvular heart disease." (PMID 40613349, 2025). "Case presentation: We describe a three-generational family affected with clinically heterogeneous LQTS type 3 and bradycardia in which a novel missense variant p.V642M in HCN4 was identified in addition to the known pathogenic variant p.E1784K in SCN5A." (PMID 40299689, 2025). "One such gene is HCN4, which encodes the hyperpolarization-activated channel and is implicated into the development of sinus bradycardia." (PMID 40299689, 2025). "Our data indicate sinus node HCN4 up-regulation as a potential mechanism underlying the protective effect of ivabradine against excessive vagal-induced bradycardia in rats." (PMID 33897414, 2021). "It is, therefore, possible that there is a training-induced downregulation of HCN4 and If in the human athlete, and this is the cause (or at least a contributing cause) of the bradycardia." (PMID 28821541, 2017). "In particular, it has become clear that HCN4 mutations are accompanied by more cardiac abnormalities than just sinus bradycardia and AF." (PMID 25642760, 2015). "We speculate that HCN4 mutations may cause the combined clinical presentation of bradycardia and structural problems of proband." (PMID 40613349, 2025). "In addition to the SCN5A finding, we discovered a previously undescribed missense variant in the bradycardia-associated gene HCN4 (NM_005477.3:c.1924G>A; NP_005468.1:p.V642M)." (PMID 40299689, 2025). "Likewise, the variant c.1979-41A>G in HCN4, the gene coding for the main channel responsible for pacemaker current and linked to different rhythm disorders, such as bradycardia, resulted related to depolarization abnormalities in patients." (PMID 36008935, 2022). "This suggests that in the human athlete, there is a downregulation of HCN4 and If, and this could be the cause (or at least a key contributing cause) of the training-induced bradycardia." (PMID 28821541, 2017). "It is known that HCN4 is essential for proper functioning and development of the cardiac conduction system, and previous studies have demonstrated that HCN4 mutations are associated with bradycardia." (PMID 27218255, 2016). "Since this patient was also symptomatic for bradycardia, a condition not normally found in LQT patients, the study explored possible changes in HCN function and found that the M54T mutation indeed causes the HCN4 current density to decrease by about 80%, in agreement with the patient’s bradycardia." (PMID 25805968, 2015). "Another study found that the HCN4 gene variant, which causes a phenotype of NCCM, bradycardia and mitral valve disease, is also associated with a larger ascending aorta." (PMID 37258990, 2023). "Training-induced bradycardia is related to intrinsic electrophysiological changes in the sinus node, with downregulation of ion channels, especially funny channel HCN4." (PMID 32560524, 2020). "Knockdown of miR-423-5p with anti-miR-423-5p reversed training-induced bradycardia via rescue of HCN4 and If." (PMID 28821541, 2017). "Our previous work on rodents was the first to attribute exercise training–induced bradycardia to the downregulation of HCN4 and If." (PMID 28821541, 2017). "The downregulation of HCN4 is linked to the upregulation of miR-423-5p in the sinoatrial node (SAN) of athletes and rodent models, while knockdown of miR-423-5p effectively reversed training-induced bradycardia in mice." (PMID 39901299, 2025). "In the human heart, HCN4 lack of function is associated with sick sinus node syndrome, bradycardia, and atrio-ventricular block." (PMID 39596280, 2024).
Bradycardia (continued). "Notably, in our patients the HCN4 pathogenic variants were associated with specific mixed phenotypes of LVNC, sinus bradycardia and substantial dilation of the ascending aorta." (PMID 35893073, 2022). "Eventually, HCN4 and the consequent If up-regulation could render the sinus node less sensitive to acute vagal inputs and protect against excessive vagal-induced bradycardia." (PMID 33897414, 2021). "Exercise training-induced bradycardia has previously been shown to result from HCN4 downregulation." (PMID 32678143, 2020). "Negative shifts of the activation range of HCN4 channels caused by specific channel mutations have often been associated with symptomatic or asymptomatic bradycardia." (PMID 30127718, 2018). "miR-423-5p contributes to training-induced bradycardia by targeting HCN4." (PMID 28821541, 2017). "However, CDR of HCN4 is crucial for determining absolute HR values and preventing bradycardia." (PMID 35556164, 2022). "In addition, the majority of the studies reported severe bradycardia and sinus dysrhythmia, suggesting that the absence of HCN4 gives rise to intrinsically reduced HRs and overshooting parasympathetic responses." (PMID 35556164, 2022).
Sinus bradycardia (23 papers, 2010 to 2026). Bradycardia related to a mean resting sinus rate of less than 50 beats per minute. "Still, some gene mutations, such as NOTCH genes, ACTC1, MYH7, MYBPC3, TTN, and HCN4, among others, have been implicated with the HCN4 gene responsible for sinus bradycardia in some patients." (PMID 39677872, 2024). "Panel sequencing showed that the two patients with clinical manifestations of sinus bradycardia, QT prolongation, and short bursts of ventricular tachycardia carried HCN4-R666Q (c.1997G > A, NM_005477) mutation in which glutamine was substituted for arginine." (PMID 36244448, 2022). "Another channelopathy is the HCN4-associated SSS which can lead to a sinus bradycardia onset in utero." (PMID 36498454, 2022). "The aim of our study was to characterize the clinical phenotype of families with LVNC and sinus bradycardia caused by the HCN4 gene alterations." (PMID 35328031, 2022). "In the present study, we described the HCN4-R666Q mutation in two sporadic patients with sinus bradycardia, QT prolongation and short bursts of ventricular tachycardia." (PMID 36244448, 2022). "Our results revealed HCN4-R666Q mutation in two sporadic patients with sinus bradycardia, QT prolongation, and short bursts of ventricular tachycardia." (PMID 36244448, 2022). "In summary, the HCN4-R666Q mutation was found in two patients with sinus bradycardia, QT prolongation, and short bursts of ventricular tachycardia." (PMID 36244448, 2022). "The only specific phenotype related to a particular gene dysfunction was observed in four patients (P2–P5), who presented with LVNC accompanied by sinus bradycardia and the dilation of the ascending aorta resulting from known pathogenic HCN4 variants." (PMID 35893073, 2022). "The aim of our study was to characterize the clinical phenotype of families with LVNC and sinus bradycardia caused by pathogenic variants of the HCN4 gene." (PMID 35328031, 2022). "As in the reports of other authors, in our patients, a significant relationship between LVNC, sinus bradycardia and HCN4 molecular variants has been demonstrated." (PMID 35328031, 2022). "In this regard, it should be noted that mutations in the HCN4 gene encoding the HCN4 channels that conduct If, were reported in patients with sinus bradycardia." (PMID 34360639, 2021). "Downregulation of the pacemaking ion channel, HCN4 (hyperpolarization-activated cyclic nucleotide gated channel 4), and the corresponding ionic current, If, underlies exercise training–induced sinus bradycardia in rodents." (PMID 28821541, 2017). "A heterozygous mutation in HCN4 was found in a family with sinus bradycardia; functional studies found decreased activity of pacemaker channels." (PMID 27182706, 2016). "Although our insights are far from complete, there are experimental data that not only relate functional loss of HCN4 to sinus bradycardia, but also to AF and AV block." (PMID 25642760, 2015). "Previous work has shown that AMP-activated protein kinase (AMPK) activation leads to sinus bradycardia, a process attributable to cardiac remodeling that involves a decrease in HCN4 membrane expression, but the mechanism underlying this event remains unclear." (PMID 41649805, 2026). "Some studies suggest that HCN4 May cause sinus bradycardia and left ventricular myocardial compaction; these two clinical abnormalities are caused by the common HCN4 gene mutation." (PMID 40613349, 2025).